RNU6-1084P (RNA, U6 small nuclear 1084, pseudogene)
Gene: Small nuclear RNA gene on chromosome 8 (11,392,411 to 11,392,517, reverse strand). Ensembl gene ENSG00000199368.
Homologues: Orthologues: chimpanzee U6 (99% identical), macaque U6 (88% identical), chimpanzee U6 (84% identical), pig U6 (84% identical), dog U6 (83% identical), pig U6 (83% identical). Paralogues in human: RNU6-1316P (90% identical), RNU6-20P (90% identical), RNU6-1145P (89% identical), RNU6-25P (89% identical), RNU6-38P (89% identical), RNU6-1 (88% identical), RNU6-1214P (88% identical), RNU6-144P (88% identical), RNU6-2 (88% identical), RNU6-35P (88% identical), RNU6-3P (88% identical), RNU6-4P (88% identical), and 1284 more.